NR4A1 (nuclear receptor subfamily 4 group A member 1)
Diseases named in the same sentence as NR4A1 in open-access papers (continued):
Sharing a sentence is not in itself a finding about the gene and the disease.
cancer (continued). "Nur77 (also known as TR3, NGFIB, or NR4A1), an orphan member of the nuclear receptor superfamily, serves as an important regulator in cancer and inflammatory diseases." (PMID 28170411, 2017). "Previous studies showed that NR4A1 in combination with p300 activated Sp-regulated genes such as survivin, bcl-2 and EGFR in cancer cells." (PMID 26035713, 2015). "Thus, inactivation of NR4A1 by the receptor antagonist DIM-C-pPhOH or the corresponding p-carboxymethyl analog (DIM-C-pPhCO2Me) decreases expression of genes associated with cell proliferation and survival, induces oxidative stress, and inhibits mTOR in cancer cell lines." (PMID 26035713, 2015). "similarly concluded that the nuclear long non-coding RNA (lncRNA) LETS1 inhibits SMAD7-induced TGF-β type I receptor polyubiquitylation through activation of NR4A1 expression in A549 cells, thereby promoting TGF-β-induced EMT migration and extravasation of cancer cells." (PMID 40666103, 2025). "DIM-3,5-Cl2 acts as an inverse NR4A1 agonist in cancer cells, and inRh30 cells, induction of proliferation by PFOS is inhibited by DIM-3,5-Cl2.Moreover, DIM-3,5-Cl2 also inhibits PFOS-induced NR4A1-regulatedPAX3-FOXO1 (FOXO1) and G9a gene products in Rh30 cells." (PMID 40066943, 2025). "This high anticancer activity suggested that other factors in addition to NR4A1 might be involved, and we recently reported that DIM-3,5 analogs were NR4A1/NR4A2 ligands that bound both receptors and inhibited cancer cell growth." (PMID 40332813, 2025). "The NR4A family (NR4A1/NUR77, NR4A2/NURR1, and NR4A3/NOR1) regulates mitochondrial function, energy metabolism, and inflammation, with implications in CVD, neurodegeneration, and cancer." (PMID 40926269, 2025). "In several cancer- and non-cancer-related diseases, NR4A1 and NR4A2 are over-expressed and are targetable with receptor agonists or inverse agonists to ameliorate disease, and there are increasing studies on development of new NR4A ligands." (PMID 40332813, 2025). "Furthermore, considering the cancer-type-dependent TME composition, further research is required to compare the efficacies of NR-V04 and NR4A1 antagonists in other cancer paradigms." (PMID 40508074, 2025). "It was demonstrated that the NR4A family has a role in T cell development from thymic differentiation to peripheral response against infections and cancer; the overexpression of NR4A1 and NR4A3, but not NR4A2, induces thymocyte apoptosis in vivo." (PMID 35407632, 2022). "Hence, overexpression of NR4A1 binds to TPβ to maintain the FAO-NADPH-ROS loop, leading to the suppression of cancer growth." (PMID 36052242, 2022). "Although the metabolic roles of NR4A1 have been reported, the diverse effects in cancer metabolic reprogramming have not been delineated." (PMID 36052242, 2022). "Various types of antitumor agents regulate apoptosis in cancer cells through NR4A1-mediated genomic and nongenomic pathways, and earlier studies of NR4A1 mainly focused on the nongenomic mechanisms of NR4A1." (PMID 35563670, 2022). "This pattern of responses observed for kaempferol in gastric cancer cells has previously been observed for CDIM/NR4A1 antagonists or NR4A1 silencing in RMS and other cancer cell lines and therefore, we hypothesized that kaempferol is an NR4A1 ligand." (PMID 34906197, 2021). "A recent work performed in a cancer line has shown that NR4A1 binds to the GC motif of the PDL1 promoter and regulates its gene expression, further supporting the possibility of a direct regulation of PDL1 expression by NR4A1 in MZB cells." (PMID 32907369, 2020). "Nuclear export of NR4A1 elicits non-genomic pro-apoptotic function in cancer cells by direct interaction with B-cell lymphoma 2 (Bcl-2) and exposure of Bcl-2 Homolog 3 domain to initiate the intrinsic apoptosis pathway." (PMID 33172112, 2020). "The mitochondrial interaction of Nr4a1 in these cancer cells was independent of its DBD, supporting previous data." (PMID 31683815, 2019).
cancer (continued). "No connection has currently been made between Nr4a1 and Creb3l1 expression in cancer cells, but there are studies that support this concept." (PMID 29311806, 2017). "NR4A1 is an NR family member that still does not have an identified endogenous ligand, and its role in cancer is also currently unclear and controversial." (PMID 28903348, 2017). "Pathway analysis of the 50 gene NIT signature revealed enrichment for MAPK signalling (DUSP1, JUN, NR4A1 and FOS), cancer specific (COX-2, PGE2, JUN and FOS), apoptosis induction (FOS and JUN) and genomic reformatting following (brain) ischaemia (EGR1 and JUN) pathways." (PMID 27384960, 2016). "NR4A1 also regulates expression of genes such as thioredoxin domain containing 5 (TXNDC5) and isocitrate dehydrogenase 1 (IDH1) to maintain low oxidative stress in cancer cells." (PMID 26035713, 2015). "Furthermore, this study reveals two potential key mechanisms by which the absence of NR4A1 expression facilitates cancer cell invasion and metastasis." (PMID 33634114, 2021). "Besides, Liu and Chen discovered that NR4A1 could be a critical general regulator in the induction of T cell dysfunction and inhibit NR4A, thus, NR4A1 was seen as promising in cancer immunotherapy." (PMID 31141819, 2019). "However, the DIM-Ph-4-X signaling pathways for cancer cell inhibition were observed to be both dependent and independent of NR4A1 and PPARγ interaction." (PMID 29861853, 2018). "Moreover, the u = mu (micro) after treatment with 20 uM DIM-C-pPhOH for 24 hr, we did not observe any nuclear export of NR4A1 which was comparable to observations in other cancer cell lines." (PMID 27144436, 2016). "Furthermore, pairwise Pearson correlation for 21/33 cancer types revealed recurrent correlation between the expression patterns for multiple class I-III NRs and retinoid X receptors (RXRs), as well as, strong positive correlation between class IV NRs (NR4A1, NR4A2, NR4A3) in 20/21 pan-cancers." (PMID 32024906, 2020). "Lack of NR4A1 in TME macrophages promotes inflammatory cytokine TNF-α production, which stimulates cancer cells to undergo EMT and promotes invasive properties." (PMID 33634114, 2021). "The orphan nuclear receptor 4A1 (NR4A1, TR3, Nur77) is overexpressed in tumors from patients with breast and several other cancers and is a negative prognostic factor for patient survival." (PMID 34072371, 2021). "Intriguingly, evidence of NR crosstalk was found between NR class IV genes (NR4A1, NR4A2, NR4A3) in 20/21 cancer types (absent in SKCM)." (PMID 32024906, 2020). "Since the role of NR4A1 in TNBC has not been specifically investigated, this study aims to define the expression profiles and specific role of NR4A1 in this highly malignant cancer." (PMID 28903348, 2017). "Hence, modulation of NR4A1 and NR4A2 expression by Rasd1 and NonO could have a major impact on the circadian control, and disruption of this process can give rise to metabolic diseases and cancer development." (PMID 21915321, 2011).
infection (34 papers, 2007 to 2025). The state of being infected such as from the introduction of a foreign agent such as serum, vaccine, antigenic substance or organism. "Infection of CD4+ T cells using lentivirus harboring sh-NR4A1 revealed that NR4A1 silencing caused the NR4A1 and BACH2 downregulation in the presence of modeling and daphnetin treatments." (PMID 41462398, 2025). "This increased bacterial burden and dissemination was associated with a reduced survival rate in Nr4a1-/- mice (14% vs. 0%) at 72 hours post-infection." (PMID 40114913, 2025). "The inhibitory effect of the modulation of NR4A1 activity on virus replication suggests its possible involvement in infection biology." (PMID 38623540, 2024). "Nr4a1-GFP levels were extremely low in all screened tissues 3 weeks into chronic infection compared to in vivo primed cells 1 day after infection." (PMID 32901001, 2020). "In the orphan NR family, all three members of Nurr family (Nr4a1, Nr4a2 and Nr4a3) exhibited repression while Rora was upregulated during later stages of infection." (PMID 29396519, 2018). "RB6-8C5 monoclonal antibody treatment depleted cells (primarily neutrophils) and led to significantly increased bacterial burden in lung and increased bacterial dissemination post-infection in both WT and Nr4a1-/- mice, reinforcing the central role of neutrophils in K. pneumoniae clearance." (PMID 40114913, 2025). "NR4A1 has been identified as an important regulator of immune and inflammatory responses, while the EphA2 gene has been shown to interfere with the response to infection in studies of host interactions with Mycobacterium tuberculosis." (PMID 39202454, 2024). "Infection with SARS‐CoV, MERS‐CoV and low pathogenic HCoV‐229E evoked a partially overlapping transcriptional response, characterised by a significant and sustained increase in expression of IEGs such as FOS, NR4A1 and FOSB." (PMID 38623540, 2024). "Firstly, the biological effect of NR4A1 on chondrocytes was investigated by Ad-NR4A1 infection." (PMID 35831280, 2022). "To verify whether NR4A1 associates with cbl‐b promoter, we infected MIN6 cells with adenovirus encoding NR4A1‐HA, and after the infection, the cells were applied for ChIP assay." (PMID 33124187, 2020). "The fast decrease of the signal could be attributed, at least at this stage (1–5 days) post infection, to signal dilution due to proliferation and/or downregulation of Nr4a1-GFP." (PMID 32901001, 2020). "Thirdly, we believe that Csn-B treatment, by increasing expression of NR4A1 in immune cells contribute to control excessive lung inflammation in infected mice by reducing production of inflammatory cytokines and by preventing the prolonged neutrophil influx in the late stage of infection." (PMID 29053748, 2017). "Next, in order to determine whether Csn-B treatment can control IAV infection, infected mice were treated daily with increasing doses of NR4A1 agonist post-infection and lung viral loads were assessed at day 5 post-infection, which corresponds to the highest replicative activity of IAV." (PMID 29053748, 2017). "Thus, selective manipulation of Nr4a1 expression may serve as a potential strategy to boost CD8 T cell response against infection and during vaccination through its manipulation of Runx3." (PMID 25762306, 2015). "Two mRNAs were down-regulated in all treatment groups at the later time points post-infection, namely, CNTNAP1 and NR4A1, while twenty mRNAs were up-regulated in all later time point treatment groups, including IFI6, LY6E, MX1, OASL, STAT1, and CMPK2." (PMID 38675946, 2024). "After infection for 48 h, the islets were treated with TG or PA for 20 h, and TUNEL assays showed that the rate of apoptotic cells is much lower in NR4A1 overexpressed islets than that of control islets infected with control virus (Ad- GFP)." (PMID 26157144, 2015).
infection (continued). "Thus, RNA sequencing analysis identified that prior to infection Nr4a1-/- neutrophils have altered antibacterial transcriptomic profiles, and that K. pneumoniae infection activates a transcriptional program that fails to enrich in the context of Nr4a1 deficiency." (PMID 40114913, 2025). "Treatment of infected cells with an NR4A1 antagonist decreased viral load, suggesting that the differential IEG gene expression may contribute to the kinetics of infection and potentially the pathogenicity of coronaviruses." (PMID 38623540, 2024). "This dataset displayed no significant increase in FOS, NR4A1 and FOSB gene expression (only a decrease at 48 hpi for FOSB) over the 96 h course of infection, like all other SARS‐CoV‐2 datasets." (PMID 38623540, 2024).
metabolic disease (21 papers, 2008 to 2026). A congenital disorder (due to inherited enzyme abnormality) or acquired (due to failure of a metabolically important organ) disorder resulting from an abnormal metabolic process. "The intricate relationship between NR4a1 and various metabolic and cellular pathways underscores its therapeutic potential, particularly in myocardial remodeling and associated metabolic disorders." (PMID 38834564, 2024). "For example, NR4A1 is elevated by stressors and inflammatory agents and levels are increased in many solid tumors, fibrosis, some cardiovascular, neuronal and metabolic diseases." (PMID 37808182, 2023). "Within the adult innate immune system and with metabolic disease, Nr4a1 plays an anti-inflammatory role." (PMID 31907354, 2020). "There is evidence that NR4A1 is important in metabolism and metabolic disease, cardiovascular and neuronal function, and inflammation in multiple tissues." (PMID 27144436, 2016). "Nuclear receptor subfamily 4 group A member 1 (NR4A1), also known as Nur77, TR3, or NGFI-B, is a member of the metabolic nuclear receptor family expressed in energy metabolism tissues such as the liver, and is associated with metabolic diseases." (PMID 38601640, 2024). "Moreover, the compound ethyl 2-[2,3,4-trimethoxy-6-(1-octanoyl) phenyl] acetate (TMPA) has demonstrated antagonistic effects on NR4a1 function in diabetic mice, offering promising avenues for metabolic disorder management." (PMID 38834564, 2024). "Thus two structurally related compounds (CsnB/TMPA) exhibit inverse activities on metabolic disease, and it is possible that the prodiabetic activity of CsnB may be due to other modes of action, such as enhancement of NR4A1 nuclear export." (PMID 40871737, 2025). "Previous studies have shown that the nuclear receptors (NRs), NR4A1 (also known as Nur77) and NR1D1, contribute to the pathology of metabolic disease through their role in ligand-dependent regulation of cellular glucose metabolism." (PMID 26556724, 2015).
inflammation (9 papers, 2016 to 2023). Aberrant reaction of the microcirculation characterized by movement of fluid and leukocytes from the blood into extravascular tissues. "If our model is correct, the interaction of Ifi27l2a and Nr4a1 would represent a novel therapeutic target for reducing brain inflammation." (PMID 36824976, 2023). "Nr4a1-GFP reporter mice were injected with PBS for control or RRV within 24 h of delivery to induce perinatal liver inflammation." (PMID 36142937, 2022).
cardiovascular disease (8 papers, 2018 to 2026). "The orphan nuclear receptor Nr4a1 has complex biological functions and has been implicated in numerous diseases, including cardiovascular disease." (PMID 39644367, 2024). "NR4A1 is associated with various hormonal, physiological, and pathophysiological diseases in humans, including metabolic disease, cardiovascular disease, apoptosis, neurodegenerative diseases, steroidogenesis, inflammation, and oncogenesis." (PMID 30013988, 2018). "The Nuclear Receptor Subfamily 4 Group A Member 1 (NR4A1), intricately associated with the pathogenesis of multiple cardiovascular diseases, has emerged as a pivotal target for the diagnosis and treatment of numerous ailments." (PMID 41943841, 2026). "Our findings concerning Sema’s modulation of NR4a1 through the Creb5 pathway offer insights into potential treatments for cardiovascular diseases, paving the way for future research in this domain." (PMID 38834564, 2024). "However, the implications of these compounds for nuclear transcription modulation of NR4a1 and their effects on nuclear translocation within the context of cardiovascular disease remain unexplored." (PMID 38834564, 2024).
kidney disease (6 papers, 2016 to 2025). "In contrast, NR4A1, as a member of the nuclear hormone receptor superfamily, contributes to the regulation of inflammation, oxidative stress, and cell apoptosis in kidney disease, with the potential to maintain the homeostasis of lymphocytes and participate in T cell differentiation." (PMID 40823027, 2025). "NR4A1 plays a significant role in kidney injury via immune activation, and enhancing NR4A1 expression or function is a potential therapeutic strategy against kidney disease." (PMID 31392215, 2019).
immune diseases (4 papers, 2017 to 2025). "As a transcription factor, NR4A1 belongs to the nuclear receptor superfamily and can be involved in cell proliferation, apoptosis, endocrine and immune diseases through a variety of pathways, and plays an important role in the development of a variety of diseases." (PMID 39736520, 2024).
psychiatric disorder (4 papers, 2018 to 2023). A disorder characterized by behavioral and/or psychological abnormalities, often accompanied by physical symptoms. "NR4A1 is a transcription factor that we found deregulated in PFC of animal models of stress and excessive CORT levels, and in humans in whom mental health diseases for which disrupted CORT levels and stress are established aggravating factors were diagnosed." (PMID 29295823, 2018).
bacterial infection (3 papers, 2024 to 2025). "Continued research into the cell- and pathogen-specific regulation by Nr4a1, along with a deeper understanding of its downstream molecular pathways, may inform the development of new immunotherapies for bacterial infections." (PMID 40114913, 2025).
neurological diseases (3 papers, 2023). "Several compounds have been found to potentially act as agonists of NR4A1, but the side effects of these compounds limit their application for neurological diseases." (PMID 37486903, 2023). "Therefore, it is important to investigate the therapeutic effects of NR4A1 manipulation in various neurological diseases and at multiple time points." (PMID 37490433, 2023).
brain disease (2 papers, 2012 to 2016). "This evidence indicates that Nr4a1 is responsible for defects caused by SNRPN knockdown and that pharmacological inhibition of Nr4a1 is a potential therapeutic target for SNRPN-related brain disorders." (PMID 27430727, 2016).
heart disease (2 papers, 2022 to 2025). "In heart disease, VD can bind to the VD receptor (VDR) in the heart to regulate the activity of NR4A1 and play a protective role." (PMID 40823027, 2025).
neurodevelopmental disorder (2 papers, 2022 to 2025). A behavioral and cognitive disorder with onset during the developmental period that involves impaired or aberrant development of intellectual, motor, or social functions. "Notably, although these genes have not been demonstrated to be directly associated with ALS in previous studies, NR4A1 and DRD4 are reported in AD, ACSL4 seems to be a biomarker of ferroptosis, and SETD1B is associated with syndromic neurodevelopmental disorder." (PMID 35873477, 2022).
blood cancers (1 paper, 2025). "Reduced expression and hyper-methylation of NR4A1 and NR4A3 are commonly encountered phenomenon in blood cancers." (PMID 40028473, 2025).
hematological cancers (1 paper, 2025). "Compounds that elevate NR4A can induce apoptosis in hematological cancers, while agents that trigger NR4A1 export from the nucleus can induce apoptosis in solid tumors." (PMID 40334012, 2025).
NR4A1 also shares sentences with these, for which no sentence is quoted: ductal carcinoma (23 papers); lobular carcinoma (20); ductal carcinoma in situ (19); invasive carcinoma (19); invasive lobular carcinoma (17); bone metastasis (14); adenocarcinoma (12); inflammatory breast carcinoma (12); breast (11); endometrioid adenocarcinoma (8); neuroendocrine tumors (8); subependymal giant cell astrocytoma (8); mucinous carcinoma (7); sarcopenia (7); meningioma (6); small cell lung carcinoma (6); adenomyosis (5); amenorrhea (5); gynecological cancers (5); migraine (5); myeloma (5); neurodegenerative disease (5); ovarian tumor (5); benign tumors (4); breast adenocarcinoma (4); carcinoma in situ (4); chronic lymphocytic leukemia (4); Crohn disease (4); endometrial tumors (4); endometrioid ovarian carcinoma (4).